OGDH (oxoglutarate dehydrogenase)
Diseases named in the same sentence as OGDH in open-access papers (continued):
Sharing a sentence is not in itself a finding about the gene and the disease.
microcephaly (2 papers, 2011 to 2023). A congenital or acquired developmental disorder in which the circumference of the head is smaller than normal for the person's age and sex. "Variants in OGDH, OGDHL, and DHTKD1 isoenzymes have been associated with various clinical phenotypes, including microcephaly." (PMID 38031187, 2023).
myocardial infarction (2 papers, 2016 to 2025). Gross necrosis of the myocardium, as a result of interruption of the blood supply to the area, as in coronary thrombosis. "Also, decreased OGDH activity in rat hearts after myocardial infarction has been observed." (PMID 28040802, 2016).
ovarian tumors (2 papers, 2016 to 2022). "To determine the positive correlation between USP13 and ACLY/OGDH levels in clinical ovarian tumours, we examined their levels using a tumour tissue microarray including 72 clinical ovarian tumour samples." (PMID 27892457, 2016). "CAOV3- and HeyA8-derived ovarian tumour growth was also greatly rescued by ACLY and OGDH overexpression." (PMID 27892457, 2016).
prostate carcinoma (2 papers, 2018 to 2020). A carcinoma that arises from epithelial cells of the prostate gland. "Most of the TCA enzymes are upregulated during the first metabolic shift in prostate cancer, and then either stay upregulated (CS, FH) or are downregulated (e.g. ACO2, OGDH, and SUCLG1) during the second shift." (PMID 29563510, 2018).
Thiamine deficiency (2 papers, 2019 to 2024). Thiamine deficiency is a condition that occurs due to not enough thiamine (vitamin B1). "Since vitamin B1 (thiamine) is essential for enzymatic activity of PDH and OGDH, thiamine deficiency decreases the activities of both PDH and OGDH, which is clinically characterized by increased plasma levels of pyruvate and lactate." (PMID 30809153, 2019). "However, a study showed that thiamine deficiency reduces mRNA levels of the enzyme transketolase and the component E1-subunit beta of the PDH, but no alteration was observed in PDHa1 and OGDH genes in three human cell types." (PMID 39364430, 2024).
Anxiety (1 paper, 2022). Intense feelings of nervousness, tension, or panic often arise in response to interpersonal stresses. "Manipulating the brain glutathione redox status by specific OGDH-directed inhibitors, we not only have reproduced the increased anxiety in the animal model but demonstrated the causal link between the OGDHC function and glutathione redox state." (PMID 35215295, 2022). "The OGDH-mediated increase in glutathione disulfide is translated into decreased glutathione redox potential in the brain, which increases anxiety and perturbs ECG." (PMID 35215295, 2022).
atherosclerosis (1 paper, 2021). A disease characterized by the build-up of fatty material and calcium deposition in the arterial wall resulting in partial or complete occlusion of the arterial lumen. "Enzymatic activity of citrate synthase and OGDH increased under the situation of atherosclerosis and chronic stress." (PMID 34539976, 2021).
bladder urothelial carcinoma (1 paper, 2022). "These were additionally narrowed down, based on the similarity between the proteomic profiles and knowledge-based immuno-expression in bladder urothelial carcinoma (green heatmap); ALDH1L1, PKP2, and OGDH were excluded due to the discordancy." (PMID 35402263, 2022).
cardiac hypertrophy (1 paper, 2020). "Our study exhibited a decrease in OGDH transcript, which, according to this paradigm, could lead to activation of AKT and subsequent cardiac hypertrophy." (PMID 32189431, 2020).
cardiomyopathy (1 paper, 2025). A disease of the heart muscle or myocardium proper. "Interestingly, changes in FGF21-responsive genes such as OXCT1, the SUCL complex, PDHA1, OGDH, ACO2, IDH3B, and ETC components (MT-CO2, COQ9, UQCRQ, SDHB/D and NDUFB7) are linked to mitochondrial deficiency syndromes manifesting cardiomyopathy and encephalopathy." (PMID 40998786, 2025).
colorectal tumors (1 paper, 2016). "These eight isoforms encoded by OGDH, COL6A3, ICAM1, PHPT1, PPP2R5D, SLC29A1, and TRIB3 genes were up-regulated in colorectal tumors, and this is in concordance with the bioinformatics data." (PMID 28105922, 2016).
epilepsy (1 paper, 2022). A brain disorder characterized by episodes of abnormally increased neuronal discharge resulting in transient episodes of sensory or motor neurological dysfunction, or psychic dysfunction. "Our findings unravel involvement of SIRT5 and OGDH in metabolic adaptation to seizures through protein acylation, consistent with the known neuroprotective role of SIRT5 and contribution of OGDH to the Glu/GABA balance perturbed in epilepsy." (PMID 36293175, 2022).
medulloblastoma (1 paper, 2021). A malignant, invasive embryonal neoplasm arising from the cerebellum. "The seven circRNAs, FKBP8, SMARCA5, GLIS1, BACH1, ZKSCAN1, CDYL, and OGDH, with a reduced expression in medulloblastoma versus cerebellum, while their corresponding linear mRNAs do not follow this change of expression pattern, were selected for further analysis." (PMID 34680287, 2021).
Sepsis (1 paper, 2023). Sepsis is defined as life-threatening organ dysfunction caused by a dysregulated host response to infection. "In the pathological state of sepsis, OGDH amplifies the inflammatory response through the MAPK pathway, releases pro−inflammatory factors, and induces acute lung injury." (PMID 36838374, 2023).
small cell lung carcinoma (1 paper, 2022). Small cell lung cancer (SCLC) is a highly aggressive malignant neoplasm, accounting for 10-15% of lung cancer cases, characterized byrapid growth, and early metastasis. "Besides ACLY and OGDH, fatty acid synthase (FASN) was recently identified as a novel substrate of USP13 in small cell lung cancer (SCLC)." (PMID 36188217, 2022).
tumor (33 papers, 2009 to 2025). "Lactylation genes, including LDHA, GLS1, and OGDH, are associated with poor immunotherapy results, are increased in malignancies, and contribute to the immunosuppressive tumor microenvironment." (PMID 39968078, 2025). "OGDHL is a component of the oxoglutarate dehydrogenase complex that is involved in degradation of glucose and glutamate, and has been associated with tumor development and progression." (PMID 38424222, 2024). "Integration with metabolomic data obtained from the same samples revealed mitochondrial dysfunction in tumour tissue through deregulation of OGDH, SDH family enzymes and PKM." (PMID 38969985, 2024). "The integration of proteomic and metabolomic data from NAT and TT using ocEAn, showed that both proteomic datasets are coherent with a tumour tissue displaying mitochondrial dysfunction, notably with deregulations of OGDH, SDH family enzymes and PKM." (PMID 38969985, 2024). "The SDH up-regulation in combination with the depletion of OGDH can well explain the depletion of succinate observed in tumours compared to healthy tissue, as illustrated by the joint up-regulation of both the abundance and ocEAn score of SDHA in TT vs. NAT." (PMID 38969985, 2024). "Conversely, low OGDH expression leads to α-KG accumulation, and knockdown of OGDH has been shown to stimulate tumor cell differentiation by increasing α-KG accumulation and inducing epigenetic modifications." (PMID 39872214, 2024). "Pyruvate dehydrogenase E1 subunit beta (PDHE1-B), 2-oxoglutarate dehydrogenase E1 (OGDH-E1), and cytochrome c oxidase subunit 2 were less-abundant proteins in the S tumor samples." (PMID 39195201, 2024). "HIF-1α facilitates ubiquitination and proteolysis of the E1 subunit of the OGDH complex, an outcome in accordance with the OGDH-E1 variation determined in this study on the surface of the tumor." (PMID 39195201, 2024). "Other enzymes crucial for the mitochondrial bioenergetics were less abundant in tumor samples, including OGDH-E1 and DLST, components of the OGDH complex, and PDHE1-B, a component of the PDH complex." (PMID 39195201, 2024). "Subunit E1 of 2-oxoglutarate dehydrogenase (OGDH-E1) was the best classifying factor for the superficial tumor region, while sorting nexin-18 and coatomer-beta protein (beta-COP), implicated in protein trafficking, classified the deep region." (PMID 39195201, 2024). "CPI-613, a lipoic acid analog, selectively inhibits pyruvate dehydrogenase and α-ketoglutarate dehydrogenase/2-oxoglutarate dehydrogenase (OGDH) in tumor cells, resulting in disruption of the Krebs cycle and ultimately leading to selective tumor cell death." (PMID 36479231, 2023). "We then treated tumor cells with RNase R (a degrader of the linear RNA) and observed that circ_0009092 was resistant to RNase R digestion compared with the linear OGDH mRNA, suggesting that circ_0009092 was more stable than liner OGDH mRNA." (PMID 38008713, 2023). "The results showed that OGDH expression in both tumour and tumour-adjacent tissues in the death group was significantly lower than that in the survival group (Supplementary eFigure 3)." (PMID 38128485, 2023). "Furthermore, CRISPR/Cas9-mediated double PDHA1/OGDH knock-down significantly reduced CD8+ T cell intra-tumoral motility as assessed using tumor slice derived from the BXPC3-NSG model." (PMID 38467616, 2024). "The development of more specific OGDH inhibitors may therefore be a desirable approach to therapeutic targeting of MYC-overexpressing tumours." (PMID 35945217, 2022). "Protein levels of USP13, ACLY and OGDH were simultaneously reduced in the Dox-treated tumours." (PMID 27892457, 2016).
tumor (continued). "In detail, the estimated IC50 levels of cisplatin were distinctly lower in low expression than in high expression of GSS, GMPPA, and OGDH, suggesting that these three genes could be used as biomarkers whose low expression indicates the tumor is more sensitive to cisplatin." (PMID 35004676, 2021). "Mechanical sponging inhibited miR‐615‐5p, allowing circ‐OGDH to release PDX1, enhancing glutamine metabolism, and supporting tumor growth in ESCC, suggesting circ‐OGDH as a promising therapeutic target." (PMID 40567251, 2025). "OGDH is regulated by Ca2+, adenine nucleotides, and NADH, and the tumor-specific isoform lacks three regions of the protein and exhibits reduced sensitivity to Ca2+." (PMID 28748451, 2018). "OGDH subunit E2, namely dihydrolipoyllysine-residue succinyltransferase (DLST), cytochrome c oxidase subunit 5B (Complex IV), and persulfide dioxygenase ETHE1 were less-abundant proteins in D tumor samples." (PMID 39195201, 2024). "OGDH activity may therefore contribute to increased TCA cycle flux, ETC function and mROS generation in tumor cells." (PMID 32059571, 2020). "Preventing the OGDH complex from entering the nucleus avoids nuclear generation of succinyl-CoA and the subsequent KAT2A-dependent H3 succinylation, reducing gene expression and inhibiting tumor cell proliferation and tumor growth." (PMID 31100940, 2019). "Whether OGDH activation by [Ca2+]m alters the epigenome in tumor cells has not been directly investigated." (PMID 32059571, 2020). "However, OGDH is the only mitochondrial enzyme that can convert α-ketoglutarate into succinyl-coA in the TCA cycle and may therefore represent a more promising therapeutic target for MYC-driven tumours." (PMID 35945217, 2022). "For Krebs cycle DH, there was a substantial decrease of isocitrate DH (IDH) and α-ketoglutarate DH (OGDH) in contrast to a modest activation of malate DH (MDH) expression, while succinate DH (SDH) and fumarate hydratase (FH) showed no statistically significant changes in expression in tumor tissues." (PMID 19558692, 2009).
cancer (25 papers, 2016 to 2025). A tumor composed of atypical neoplastic, often pleomorphic cells that invade other tissues. "Together, these results indicated that the UBE2F reporter should be informative for testing splicing outcomes of cancer-associated RRM mutations in both proteins while OGDH is suitable for examining PUF60 variants." (PMID 32664474, 2020). "Finally, knockdown of OGDH was associated with profound growth defects in a subset of cancer cell lines, potentially providing a therapeutic target in a metabolically distinct subset of tumors, although the distinct function of mRNA isoforms was not addressed." (PMID 32664474, 2020). "Indeed, several somatic mutations in LIAS or OGDH have been collated (Catalogue of Somatic Mutations in Cancer [COSMIC] database), and a number of the LIAS mutations are similar to the known homozygous mutations, which tend to occur around the Fe-S cluster coordination sites." (PMID 27923773, 2016). "OGDH expression and activity are commonly upregulated to adapt to the increased glycolytic capacity of cancer cells." (PMID 39872214, 2024). "It was recently found that the proliferation and survival of cancer cells carrying a PIK3CA mutation, as is HT29, is sensitive to the TCA cycle enzyme 2-oxoglutarate dehydrogenase (OGDH)." (PMID 37512582, 2023). "Since α-KG, but not NAC supplementation, partially prevents the cytotoxic effects of FRI-1, and lipoic acid increases the cell death, OGDH inhibition emerges as an essential step for the anti-cancer effect of FRI-1." (PMID 34679752, 2021). "USP13 upregulates ACLY and OGDH, two key regulators that drive glutaminolysis, ATP generation and lipid synthesis in cancer metabolism." (PMID 27892457, 2016). "Targeting OGDH, whose expression is upregulated in different types of cancer to enhance mitochondrial metabolism, might represent a specific approach to fight the progression of EAC cases showing a similar mutation pattern." (PMID 40725116, 2025). "Moreover, different factors during cancer growth, such as decreases in glucose-derived citrate, defective OGDH complexes, and isocitrate dehydrogenase, great glutamine demand, and the glutaminolysis process, support the reductive glutamine metabolism." (PMID 39195201, 2024). "OGDH complex dysregulation contributes to increased ROS levels and interrupts substrate fluxes, leading to the production of oncometabolites, such as L-2-hydroxyglutarate, during the process of cancer pathogenesis and development." (PMID 39195201, 2024). "Therefore, OGDH has a crucial role in regulating metabolism and the epigenetic signature of cancer cells, which mainly depends on affecting α-KG contents." (PMID 39872214, 2024). "Furthermore, overexpression of SIRT5 inhibits oxoglutarate dehydrogenase (OGDH), which in turn lowers ATP levels and raises ROS levels, thereby impairing the proliferation and migration of cancer cells." (PMID 36980194, 2023). "Similarly, in a recent study, cancer cells have been found to display a wide range of sensitivities in response to OGDH knockdown, in vitro and in vivo, suggesting a probable therapeutic target in cancer management." (PMID 33937086, 2021). "Impaired alternative splicing of UBE2F, GANAB or OGDH in vivo may be important for cancer initiation or progression." (PMID 32664474, 2020). "Both ACLY and OGDH are key metabolic enzymes that drive cancer cell proliferation." (PMID 27892457, 2016). "The siRNA-mediated knockdown of its subunits, DLD, DLST, and OGDH, substantially repressed the growth of COX7RP-overexpressing cancer cells in both hypoxic and normoxic conditions." (PMID 31511525, 2019). "Clearly, both OGDH and ACLY are essential to maintain cancer cell proliferation by maintaining lipogenic acetyl-CoA pools." (PMID 27892457, 2016). "To further clarify the effects of OGDH and ACLY on de novo fatty acids synthesis in OVCA, we used [U-13C5] glutamine or [U-13C6] glucose to culture cancer cells for 72 h." (PMID 27892457, 2016).
cancer (continued). "Thus, a pharmacological approach targeting OGDH dependency in these subsets of cancers is still lacking." (PMID 34827664, 2021).
Neurological disorders (4 papers, 2016 to 2023). "Neurological disorders are caused by a decrease in the activity of OGDH and the reactive oxygen species (ROS)-induced inactivation of OGDH in brain." (PMID 34884868, 2021). "Recently, a biallelic pathogenic variant in OGDH gene leading to deficient 2-oxoglutarate dehydrogenase (E1o, the first component of the OGDHc, also known as OGDH) was reported in individuals with a neurological disorder resembling mitochondrial disease." (PMID 33946784, 2021). "Interestingly, OGDH, OGDHL, and DHTKD1 each possess a ThDP binding domain, and thiamine (vitamin B1) administration is an intriguing treatment possibility, as oral thiamine has been used to improve various neurological disorders with minimal adverse reactions." (PMID 38031187, 2023).
movement disorder (3 papers, 2023 to 2025). Neurological conditions resulting in abnormal voluntary or involuntary movement, which may impact the speed, fluency, quality and ease of movement. "In humans, OGDH deficiency causes movement disorders and hyperlactatemia." (PMID 40904733, 2025).
infection (2 papers, 2024 to 2025). The state of being infected such as from the introduction of a foreign agent such as serum, vaccine, antigenic substance or organism. "Our study observed a significant upregulation of intracellular OGDH expression during the early stages of infection with the Cm TC0668wt strain, followed by a decrease in later stages." (PMID 41081600, 2025). "The Cm TC0668wt strain was more effective at upregulating OGDH expression compared to the Cm TC0668mut strain, with notable effects seen after 12 hours of infection in HeLa cells and 24 hours in HUVECs." (PMID 41081600, 2025). "We observed that in HeLa cells and HUVECs infected with the Cm TC0668wt strain, the TCA cycle-related protein OGDH increased progressively in the early stages of infection but decreased in the later stages." (PMID 41081600, 2025).
neurodevelopmental disorder (2 papers, 2023). A behavioral and cognitive disorder with onset during the developmental period that involves impaired or aberrant development of intellectual, motor, or social functions. "We established that biallelic variants in OGDH cause a neurodevelopmental disorder with metabolic and movement abnormalities." (PMID 36520152, 2023). "We identified 4 unrelated individuals harboring homozygous variants in OGDH, a gene recently implicated in a single family with α-KGDH deficiency, a severe neurodevelopmental disorder." (PMID 36520152, 2023). "Going further, we uncovered evidence for a complex compensatory relationship among OGDH, OGDHL, and DHTKD1 isoenzymes that are associated with neurodevelopmental disorders and exhibit complex transcriptional compensation patterns with partial functional redundancy." (PMID 38031187, 2023).
neurodegenerative disease (1 paper, 2023). A disorder of the central nervous system characterized by gradual and progressive loss of neural tissue and neurologic function. "Previous research demonstrated the crucial role of OGDH in neuronal cell death, which is associated with neurodegenerative diseases." (PMID 38031187, 2023).
OGDH also shares sentences with these, for which no sentence is quoted: Leigh disease (3 papers); Obesity (3); Dystonia (2); hepatocellular carcinoma (2); metabolic disorders (2); adrenal gland diseases (1); anisakiasis (1); benign prostate hyperplasia (1); brain tumor (1); colon tumors (1); Encephalopathy (1); genetic disorders (1); Hyperglycemia (1); kidney cancer (1); mammary adenocarcinoma (1); mitochondrial disease (1); multiple myeloma (1); psychiatric disorder (1); Seizure (1); urothelial carcinoma (1).